DRD2 (dopamine receptor D2)
Diseases named in the same sentence as DRD2 in open-access papers (continued):
Sharing a sentence is not in itself a finding about the gene and the disease.
schizophrenia (continued). "DRD2 is distributed at high levels in the striatum, nucleus accumbens and olfactory tubercle, as well as in the dopaminergic neurons in the mesolimbic pathway projecting from the ventral tegmental area to nucleus accumbens, which is closely related to positive symptoms in schizophrenia." (PMID 26694375, 2015). "Loxapine succinate is a dopamine receptor D2 (DRD2) antagonist, and has been approved by the United States Food and Drug Administration (US FDA) for use as a therapeutic agent in patients with schizophrenia." (PMID 38478584, 2024). "Here we examined the relative expression of DRD1, DRD2 and IDO1 and IDO2 genes transcription in MK-801 model schizophrenia group and T. gondii infected rat brain and subsequent neurotransmitter changes." (PMID 36950587, 2023). "The dopamine D2 receptor (DRD2), a crucial element in the dopaminergic system, is one of the direct targets in treating schizophrenia." (PMID 35563106, 2022). "In conclusion, the DRD1, DRD2, and GSK3 were expressed differentially between the schizophrenia patients and the healthy controls." (PMID 35062349, 2022). "In this article, our data displayed an elevated DRD2 and a marked consistency between HERV-W ENV and DRD2 in schizophrenia." (PMID 35062349, 2022). "In summary, this evidence suggested that DA, DRD2, and HERV-W ENV, which were all markedly upregulated, showed a marked consistency in schizophrenia patients." (PMID 35062349, 2022). "A large number of studies have focused on the function of dopamine receptor D2 (DRD2) in central nervous system disorders, such as movement disorders, schizophrenia, migraine, and posttraumatic stress disorder." (PMID 36079577, 2022). "Variations in the Drd2 gene have clinical significance since DRD2 is a pharmacotherapeutic target for treating psychiatric disorders like ADHD and schizophrenia." (PMID 34853389, 2021). "Another research was done in 2020 to study the effect of rs1076560 (dopamine receptor D2 or DRD2) and rs4680 (COMT Val158Met) on tardive dyskinesia and cognition in schizophrenia patients." (PMID 34725583, 2021). "The D2 dopamine receptor (DRD2) was identified as one of the top ranked genes and has been widely studied in schizophrenia, for which SNPs located in the gene promoter affect its transcriptional activity." (PMID 33827428, 2021). "Convergent evidence suggests that GSK3 is an important mediator of the DRD2-βArr2-AKT-GSK3 signaling pathway and that GSK3 plays critical roles in brain development and schizophrenia pathogenesis." (PMID 31959776, 2020). "Three SNPs, i.e., rs1799732 and rs6276 located within DRD2, and rs1800497 within ANKK1, were identified in the DNA samples of 198 schizophrenia probands, including 103 patients with deficit (DS) and 95 patients with non-deficit schizophrenia (NDS)." (PMID 32565876, 2020). "Candidate gene studies have often been focused on the role of dopamine receptors and related genes (namely DRD1, DRD2, DRD3, DRD4, and DRD5) as modulators of antipsychotic drug responsiveness and schizophrenia symptoms." (PMID 30687136, 2018). "Parallel and multistep analysis in this research showed that SLC1A1, DRD2, DRD4, BDNF, ESR1, CDH2, GRIN2B, TNFa, GABBR1, and OLIG2 are common genes between schizophrenia and OCD which ESR1, DRD2, GABBR1, TNFa, and CDH2 are the most important individuals." (PMID 31086558, 2018). "The main finding of this exploratory study involves rs6275 and rs2242592 of the DRD2/ANKK1 locus and Stroop Color-Word in schizophrenia." (PMID 28085950, 2017). "For example, TH was related to essential hypertension; DRD2 to childhood temperament, extraversion, and antisocial behavior; and neurotensin genes (NLN, NTSR1, NTRS2) to schizophrenia and memory consolidation." (PMID 26308205, 2015). "Spearman rank correlations analysis between DRD2, DRD3, and DARPP-32 mRNA levels and five factors of the PANSS in patients with psychotic disorder NOS and the schizophrenia/schizophreniform disorder group." (PMID 26561806, 2015).
schizophrenia (continued). "In Phenopedia, the most reported schizophrenia-related gene was COMT, which was supported by 278 publications; whereas DRD2 and BDNF are supported by 139 and 116 publications respectively." (PMID 25522158, 2014). "The correlation between DRD2 mRNA levels in PBLs and the positive symptom points of PANSS in acute schizophrenia patients was significant (r = 0.443, p = 0.044)." (PMID 24086483, 2013). "Identifying the cellular localization of this up-regulation of DRD2 would be important for determining whether the increased DRD2 is perhaps counteracting DRD1 effects on pyramidal neurons or bolstering the inhibitory drive of interneurons in schizophrenia prefrontal cortex." (PMID 23720610, 2013). "Correlation analysis between DAT and DRD2 mRNA levels and PANSS scores in schizophrenia patients (r value)." (PMID 24086483, 2013). "In addition, a recent meta-analysis was performed that was based on over 1000 association studies on schizophrenia, and this study highlighted 16 genes, which were mostly dopamine-related, including catechol-O-methyltransferase (COMT) and dopamine receptors D1, D2, and D4 (DRD1, DRD2 and DRD4)." (PMID 24086483, 2013). "The network also includes some well-studied schizophrenia candidate genes (e.g., BDNF, DRD2, GRIN1 and GAD1)." (PMID 20156358, 2010). "Risperidone is a remarkable antagonist of 5HT2A serotonin and dopamine receptor D2, and its lower doses can alleviate the negative effects of schizophrenia." (PMID 37042060, 2023). "The encouraging therapeutic potential of TAAR1 agonists as the first antipsychotic drugs without DRD2 blocking action to treat schizophrenia has been demonstrated in clinical trials." (PMID 35053262, 2022). "So far, many authors have analyzed the relationship between DRD2 haplotype and alcohol, nicotine, or drug addiction; some types of cancer; and psychiatric disorders such as ADHD or schizophrenia; confirming that this type of analysis is more informative and provides new associations." (PMID 35564336, 2022). "In this work, we analyzed 28 studies conducted from 1989 to 2021, studying 37 genetic variations, including SNVs/polymorphisms of four candidate dopamine receptor genes (DRD1, DRD2, DRD3, DRD4) involved in the development of AIP and AITD in patients with schizophrenia." (PMID 34440083, 2021). "In addition, a separate analysis of this patient subgroup showed that the DRD2 rs6276 G allele was significantly more frequent in patients with DS compared to NDS, which may suggest its associations with inherited susceptibility to schizophrenia and its DS phenotype." (PMID 32565876, 2020). "A genome-wide association study recently showed that multiple genes involved in the glutamatergic system and the DRD2 gene in the dopamine system acted on schizophrenia, implying that the two systems do not work independently in schizophrenia." (PMID 30704411, 2019). "Four candidate genes (DRD2, COMT, 5-HTR2A, and SLC6A4) from dopaminergic and serotoninergic pathways have received the most attention in the literature and have been supposed as the promising candidate genes for schizophrenia and treatment response." (PMID 30483162, 2018). "Some authors reported the up-regulation of DRD2 mRNA expression and DRD2 binding in lymphocytes from schizophrenia patients, although other studies have not confirmed these findings." (PMID 28358316, 2017). "In addition, they noted a correlation between DRD2 mRNA levels and positive scores on the PANSS—but only in acute schizophrenia patients." (PMID 27795960, 2016). "Interestingly, HNRNPH1 binding affinity and splicing can be modulated by genome-wide significant SNPs associated with bipolar disorder, major depressive disorder, and schizophrenia, including rs1006737 (CACNA1C), rs2251219 (PBRM1), and rs1076560 (DRD2)." (PMID 26658939, 2015).
schizophrenia (continued). "Although the dopamine D2 receptor (DRD2) has been a main target of antipsychotic pharmacotherapy for the treatment of schizophrenia, the standard treatment does not offer sufficient relief of symptoms to 20%–30% of patients suffering from this disorder." (PMID 26694375, 2015). "However, the gene expression levels of DRD2 and DAT in PBLs of schizophrenia patients and their relationship with clinical symptoms have not been reported in many studies." (PMID 24086483, 2013). "Among these 16 SZGenes, several (DRD2, GRIN1, GRM7 and GAD1) are related to three neurochemical hypotheses in the molecular mechanisms of schizophrenia, i.e., the dopamine, glutamatergic and GABAergic hypotheses." (PMID 20156358, 2010). "Some of the potential loci that may be affected by methylation in schizophrenia include SOX 10, COMT and DRD2, but the direct role of the gene specific methylation in schizophrenia has not been established." (PMID 19102774, 2008). "Those cerebellum-specific miRNAs may reflect cerebellar abnormalities in schizophrenia such as a reduced cerebellar expression of the Sp transcription factors and dopamine receptor D2, both of which are related to negative symptoms." (PMID 38673876, 2024). "Additionally, there is currently no report on detecting the protein levels of serum DRD2 in schizophrenia." (PMID 35062349, 2022). "Research into the pharmacogenomic influence is however nascent, with most of the focus being on the relationship with cannabis dependence (e.g. CNR1 receptor SNPs which shows no obvious association), or schizophrenia (COMT, DRD2 SNPs showing a stronger correlation)." (PMID 31948424, 2020). "Given that we observed a late-born PV interneuron population derived from Nkx6.2 populating preferentially the PFC and not the ventral subiculum, we asked whether the deletion of DRD2 from this subpopulation of neurons might reproduce domain-specific phenotypes within schizophrenia pathophysiology." (PMID 37945756, 2023). "The reduced pre-adolescent expression of Drd2 in both investigated brain areas might be interpreted as downregulation, eventually indicating dopaminergic overstimulation from the VTA, which is in line with the dopamine hypothesis of schizophrenia, at least in the case of CING." (PMID 36481661, 2022). "However, enduring negative and cognitive symptoms of schizophrenia, resistant to DRD2 antagonist treatment, suggested that they might be due to a deficit in the prefrontal cortex (PFC) DA transmission at DRD1." (PMID 28358316, 2017). "Therefore, DRD2 mRNA levels in PBLs might be a state index related to psychiatric symptoms, but not a quality index related to schizophrenia." (PMID 24086483, 2013). "Antipsychotic drugs, which antagonize DRD2 (with or without 5‐HT2A receptor inhibition), have been used against the positive symptoms of schizophrenia." (PMID 36794530, 2023). "Dopamine receptor D2 short, vesicular monoamine transporter (VMAT2) and DAT mRNAs were significantly decreased in schizophrenia, with no change in DRD3 mRNA, DRD3nf mRNA and DAT protein between diagnostic groups." (PMID 28094812, 2017). "We found a significant positive correlation between the DRD2 mRNA level and the score of the excited factor of the Positive and Negative Syndrome Scale (PANSS) in patients with schizophrenia/schizophreniform disorder." (PMID 26561806, 2015). "Secondly, the expression level of DRD2, PI3KCB, and AKT1 in peripheral blood may not an index of schizophrenia, but only an index of psychiatric symptoms." (PMID 29156812, 2017).
depression (136 papers, 2008 to 2026). "BDNF, which is crucial for neuronal survival and plasticity, is linked to mood disorders and suicide risk, while DRD2, involved in dopamine signaling, affects mood regulation and susceptibility to depression and suicidal tendencies." (PMID 39940809, 2025). "Dopamine signaling is influencedby the dopamine receptor D2 (DRD2) NcoI C/C genotype which shows asignificant association with migraine, depression, and anxiety." (PMID 40129424, 2025). "We have recently reported the implication of DRD2 gene in the risk of T2D and depression in the same multigenerational Italian families under study." (PMID 37563671, 2023). "For example, depression is associated with higher DRD2/3 availability (11C‐raclopride BP) in putamen region." (PMID 37699864, 2023). "Drug–gene interaction studies highlight antipsychotics, estrogen-related drugs, DRD2-targeting drugs, calcium channel modulators, and serotonin receptor antagonism as potential drugs to counteract transcriptional effects of depression risk." (PMID 37076454, 2023). "We recently identified PRL as a gene contributing to PCOS risk and reported DRD2 conferring risk for type 2 diabetes and depression, which can both coexist with PCOS." (PMID 37563671, 2023). "Recently, an increasing number of articles have highlighted the ability of both DRD1 and DRD2 to form heterodimers, and a growing body of evidence has linked D1-D2 heterodimers to drug addiction, Parkinson’s disease, schizophrenia, depression, and anhedonia." (PMID 36059987, 2022). "In fact, in terms of major depression, transcriptome-wide association research analyses of major depression indicated significant correlations with the expression of DRD2 in the nucleus accumbens (NAc) and NEGR1 in the hypothalamus, among others." (PMID 36294858, 2022). "An approach using PET has suggested that deep brain stimulation (DBS) of the medial forebrain bundle (MFB) partially reverses depression-like phenotypes associated with DRD2 blockade." (PMID 36059987, 2022). "(2015) found that toddlers with at least one A1 allele of DRD2 or with the 10/10 genotype of SLC6A3 had blunted reactive salivary cortisol if their mother had higher depression." (PMID 36282746, 2022). "The vulnerability to depression and reactivity of antidepressants are associated with DRD2 gene polymorphisms." (PMID 34976096, 2021). "A biologically based study showed that a specific dopamine D2 receptor genotype (DRD2 NcoI allele) was associated with comorbid migraine with aura, major depression, and generalized anxiety disorder." (PMID 30941087, 2019). "Carriers of the A1 allele of the Taq1A drd2 polymorphism have lower levels of D2 receptor binding and this is implicated in depression symptomatology." (PMID 25806005, 2015). "Further, the association between smoking cessation and lifetime depression was significantly modified by DRD2/ANKK1 rs1800497 genotype." (PMID 24927283, 2014). "Drd2 is a G protein-coupled receptor that binds to dopamine and transmits signals, and its upregulation is associated with hyperactivity, while its downregulation can lead to motor impairments, as well as depression and attention deficits." (PMID 40806421, 2025). "A multi-ancestry GWAS identified 53 novel Depression risk loci, with fine-mapping and multi-omics integration pinpointing 43 high-confidence genes including DRD2 (dopamine receptor D2) and mitochondrial gene NDUFAF3, revealing substantial ancestral heterogeneity in genetic architecture." (PMID 40508038, 2025). "The expression of striatal DRD1 was significantly decreased, while DRD2 expression was dramatically increased in the aged WDR45cKO mice, which may be associated with depression-like behavior." (PMID 39183331, 2024). "In addition, large GWAS from Yale recently revealed that for example, in 1.2 million veterans, the top candidate gene to associate with depression was the DRD2 gene polymorphism tested in GARS was at 1 × 10−7." (PMID 37511777, 2023).
depression (continued). "Enhanced DRD2 promoter methylation and subsequent downregulation of DRD2 expression in the ventral tegmental area may be involved in the increase in susceptibility to depression." (PMID 35308874, 2022). "This indicates that mutation of the DRD2 gene may render the person less susceptible to depression through thickening the triangular part of the inferior frontal gyrus." (PMID 33690643, 2021). "Therefore, the observed alterations in miR-504, DRD1, and DRD2 expressions should only be associated with depression-like phenotype." (PMID 23922862, 2013). "However, the molecular mechanisms underlying decreased DRD1 and DRD2 expression in stress-induced depression have yet to be fully elucidated." (PMID 23922862, 2013). "Importantly, impaired DRD2-mediated signaling by functional defects in the Par-4 protein has been associated with depression-like behavior in animal models." (PMID 23029138, 2012). "Therefore, DRD2 and β-catenin serve as crucial factors mediated glioma progression caused by chronic stress and the combined detection of DRD2 and β-catenin may be a key way for predicting prognosis of glioma patients with depression." (PMID 37415171, 2023). "Another top finding from the TWAS analysis was DRD2 (D2 dopamine receptor) with a significantly predicted decreased expression in the nucleus accumbens, which is a drug target and critical part of the mesolimbic dopamine reward circuit that has long been implicated in depression." (PMID 35456452, 2022). "Enhanced DRD2 promoter methylation in the VTA may increase the susceptibility to depression." (PMID 35308874, 2022). "Collectively, these findings underscore the pivotal role of the PPARγ-DRD2 pathway in D2-MSNs in modulating depression-like behaviors." (PMID 41510157, 2026). "Our data show that GlcCer, which enhances endogenous PPARγ-DRD2 signaling, is a promising therapeutic strategy for treating depression." (PMID 41510157, 2026). "In particular, a significant association exists between genetic variations in the dopamine D2 receptor (DRD2) gene and increased susceptibility to migraine with aura (MWA) and major depression." (PMID 40634879, 2025). "This genomic region that harbors multiple known depression-associated genes (e.g., NCAM1, TTC12, DRD2) remained significant for depression and ischemic stroke." (PMID 40949012, 2025). "Another study from Guo and colleagues (2022) investigated the effect of DNA methylation of the dopamine D2 receptor (Drd2) in the VTA on ELS-induced depression in adult rats." (PMID 39457754, 2024). "DRD2 (encoding D2 dopamine receptor), located in the same region, has been suggested to play an important role in the pathogenesis of anxiety and depression, and psychological stress drives the development of malignancy via DRD2 signaling." (PMID 40226707, 2024). "In summary, Rasd2 plays a role in depression-like behavior induced byovariectomy, and this role is related to the regulation of DRD2." (PMID 36566472, 2023). "Genome-wide association studies found substance use disorder and depression are frequent comorbidities, and significant correlation with NEGR1 expression in the hypothalamus and DRD2 in the NAc." (PMID 38164471, 2023). "Remarkably, patients with high-depression exhibited high DRD2 and β-catenin levels, which showed poor prognosis." (PMID 37415171, 2023). "Of note, we also reported DRD2 and PRL-variants conferring risk for type 2 diabetes and depression, which can both coexist with PCOS." (PMID 37563671, 2023). "Except for that glioma patients with high depression tended to have a worse prognosis than those with less depression, we further found that DRD2 and β-catenin were upregulated in glioma tissues from patients with depression." (PMID 37415171, 2023). "Important genes involved in neurotransmitter transmission in these pathways include ACHE, MAOA, and DRD2 are related to the development of depression." (PMID 36072347, 2022).